SPACDR (sperm acrosome developmental regulator)
Description:
May play a role in acrosome formation and nucleus shaping during spermiogenesis.
Synonyms: C7orf61; IMAGE:4839025
Tractability: No criterion of Open Targets' tractability assessment is met for any kind of drug.
Gene: Protein-coding gene on chromosome 7 (100,456,620 to 100,464,260, reverse strand). Ensembl gene ENSG00000185955.
Subcellular location: Cytoplasmic vesicle, secretory vesicle, acrosome
Subcellular location (Human Protein Atlas): Acrosome; Vesicles
Gene Ontology:
Biological process: spermatid development
Cellular component: acrosomal vesicle; nucleus
Genetic constraint (gnomAD): Loss-of-function variants: 10 observed, 25.94 expected, observed/expected ratio (o/e) 0.39, 90% interval 0.24 to 0.65. The upper end of that interval is the gene's LOEUF score, 0.65, which puts it in group 2 of 6, group 1 being the genes least tolerant of losing a copy. Missense variants: 217 observed, 265.2 expected, observed/expected ratio (o/e) 0.82, 90% interval 0.73 to 0.92. Synonymous variants: 88 observed, 113.31 expected, observed/expected ratio (o/e) 0.78, 90% interval 0.65 to 0.93.
Homologues: Orthologues: chimpanzee SPACDR (99% identical), pig SPACDR (64% identical), rabbit SPACDR (61% identical), mouse Tsc22d4 (46% identical).
Diseases named in the same sentence as SPACDR in open-access papers:
SPACDR is named in the same sentence as 2 diseases in open-access papers, as found by Europe PMC text mining. Sharing a sentence is not in itself a finding about the gene and the disease.
SPACDR shares sentences with these, for which no sentence is quoted: Globozoospermia (2 papers); cancer (1).